CD14 (CD14 molecule)
Diseases named in the same sentence as CD14 in open-access papers (continued):
Sharing a sentence is not in itself a finding about the gene and the disease.
tumor (continued). "Thus, the mechanisms possibly underlying the pro-tumoral action of CD14+ cDCs are likely to acquire the function of tumor-associate macrophages (TAM), which are thought to promote tumor cell growth." (PMID 35454882, 2022). "The identification of immunosuppressive CD14+ cells in the blood and tumour of CRC patient raised the question as to whether these cells could be defined as M-MDSCs, which are characterized by reduced HLA-DR expression." (PMID 34727230, 2022). "The relationship between CD14 and tumor formation is complex." (PMID 35387121, 2022). "Thus, tumour cell components accumulate in the activated macrophages and can then be extracted from the peripheral blood and analysed e.g. by flow cytometry via CD14 and CD16." (PMID 35864157, 2022). "While CD14+ cells within the TME may be a common target across patients and treatments, the full breadth of mechanisms that drive tumor survival through cross-talk with CD14+ cells remains an active area of investigation." (PMID 36139660, 2022). "All tumor cell type-derived factors induced the co-expression of CD14 and DC-SIGN." (PMID 36194602, 2022). "Since activated macrophages (CD14+/CD16+) phagocytose entire tumour-derived protein epitopes, other tumour-associated proteins may be detected via EDIM technology using specific antibodies as well." (PMID 35864157, 2022). "Together, these data highlight the variety of the potential avenues through which CD14+ cells within the TME may promote tumor cell survival." (PMID 36139660, 2022). "The unique high expression level of S100A8 in the CD14 cell cluster indicates that the CD14 cells may play pro-inflammatory and anti-tumor roles in ccRCC." (PMID 35812372, 2022). "To explore the possible role of CA12 in tumor-associated monocytes and macrophages, we treated peripheral CD14+ cells with HepG2 TSN in the presence of negative control siRNA (siNC), CA12 siRNA (siCA12)." (PMID 35362480, 2022). "Furthermore, NETs stimulated CD3+ and CD14+ cell infiltration into the tumor, indicating that NETs can boost anti-tumor immune responses in the tumor microenvironment through the induction of T cells and macrophage infiltration." (PMID 36555469, 2022). "The IHC for CD14 expression demonstrated that all the tumor specimens contained CD14+ cells." (PMID 36139660, 2022). "Finally, since MDSCs have been shown to suppress the T-cell mediated anti-tumor response in MM, we analyzed CD14+ and CD14− MDSCs in these BM samples." (PMID 34070044, 2021). "In addition, myeloid cell densities in the tumor compartment were found to differ significantly based on differentiation grade (CD14 p = 0.001; CD68 p < 0.001; CD163 p < 0.001)." (PMID 34194435, 2021). "However, CD14 was recently described as a marker to distinguish PMN-MDSCs from classical neutrophils in tumor-bearing mice." (PMID 34944914, 2021). "Based on bulk RNA data from the TCGA cohort, the highest levels of wild-type CYSLTR2 expression were observed in tumours with an inflammatory phenotype as shown by their immune gene expression signature (high expression of CD14, CD163 [monocytes/macrophages] and CD3D, CD8A [T cells])." (PMID 33588787, 2021). "We sought to determine if EwS EVs may play a role in the observed accumulation of immunosuppressive M2 macrophages and CD14+HLA-DRlow/neg monocytes in the tumor microenvironment and blood circulation of EwS patients." (PMID 34440851, 2021). "Therefore, we sought to assess TREM-1 expression on CD14+ monocytes and on neutrophils in peripheral blood and/or tumor tissues of patients with RCC." (PMID 35223446, 2021). "Whether the subset of monocytes with elevated m6A levels had a similar role in tumor immunotherapy to the CD14+CD16+HLA-DRhi subset deserves further investigation." (PMID 34659267, 2021).
tumor (continued). "Among myeloid cell types in the tumor, monocyte-derived macrophages, defined by markers such as CD14, CSF1R and LGMN and dendritic cells were increased, while tissue-resident macrophages and monocytes were decreased, which we also observed in an independent dataset." (PMID 34663877, 2021). "We noted an increased CD11b+/Ly6C+/CD14+ population (mMDSC or monocytic/macrophagic myeloid-derived suppressor cells), both as a percentage of parental population (CD11b+) and in total cell numbers, in KO tumor CD45+ cells." (PMID 34768912, 2021). "In addition, the percentages of various CD14+ macrophage subsets in the tumor were lowered, whereas the cytokine-producing NK cells, but not the cytotoxic NK cells, were increased statistically." (PMID 32331230, 2020). "In a study of 311 BC patients of Swedish cohort flow cytometry analysis revealed higher percentage of tumor-infiltrating CD45+CD11b+CD14+ macrophages from women who received NAC (paclitaxel and fluorouracil–doxorubicin–cyclophosphamide) compared to the tumors from women treated with surgery alone." (PMID 33194645, 2020). "All tumor-bearing lungs contained some monocytes and/or macrophages (CD14+CD88+)." (PMID 32610077, 2020). "Gene expression of CD14 was likewise decreased in all investigated cell fractions from tumor tissues (UICC stages I–III) when treated with KMP01D alone or in combination with vitamin D3 (KMP01D and combination of KMP01D and vitamin D3 vs. untreated cells: UICC I–III: p < 0.0001)." (PMID 32425932, 2020). "However, solid tumors were observed in xNSG mice that had been transplanted with CD14+ cells collected at advanced tumor stages (229 ± 88.9 mm3)." (PMID 32824016, 2020). "(B) Representative immuno-histochemical staining of Neu and CD14 in a Neu tumor." (PMID 32840210, 2020). "Additionally, we detected accumulation of CD45+CD14+PD-L2+ cells in the tumor and PF in comparison to PB." (PMID 33062717, 2020). "Therefore, our findings suggest that the close proximity between monocytic myeloid and cytotoxic T cells reflects tumor stromal co-localization of CD11b+CD14+ myeloid cells with CD8+TCF7+ stroma-residual stem cell-like T cells." (PMID 33193316, 2020). "In particular, CD45− cells (tumour and stromal populations) were injected in a dermal scaffold, and cultured for 48 h; followed by injection of autologous blood circulating CD14+ monocytes (as a source of myeloid immune cells) and an additional 2day culture period." (PMID 32488012, 2020). "This suggested that NK cells acquired CD14 by trogocytosis on tumor AML cells as they gained CD33." (PMID 33276644, 2020). "Bulk RNA-seq analysis of CD1c+CD14+ cells sorted from tumor-invaded lymph nodes indicated that they displayed a similar expression profile as blood DC3s (high expression of cDC2 markers such as CLEC10A and FCER1A combined with low expression of monocyte-associated markers such as C5AR1 and SOD2)." (PMID 32610077, 2020). "Monocytes after membrane fusion with TEX gain a new phenotype without human leukocyte antigen-DR (HLA-DR) expression and costimulatory molecule upregulation but with CD14 expression, called CD14+HLA-DRlo/neg monocytes and have emerged as important mediators of tumor-induced immunosuppression." (PMID 32537468, 2020). "Tumor stage-related changes in the properties of CD14+ cells were examined." (PMID 32824016, 2020). "However, even when the heterogeneity of CD1c+ cells is appreciated, including recruitment of CD14+CD1c+ DCs in tumor-draining lymph nodes, little is known about the function of CD1c+ subtypes." (PMID 32610077, 2020). "TAMs can differentiate from circulating blood CD14 monocytes or from tumor-recruited MDSCs." (PMID 31811337, 2020). "ULMs are also conspicuously devoid of HLA-DR+ CD14− dendritic cells and tertiary lymphoid structures, thus an adaptive response may occur in tumor-draining lymph nodes." (PMID 31959856, 2020).
tumor (continued). "Moreover, although IL-10 (189 ± 78 pg/mL) and CCL1 (3.2 ± 1.9 ng/mL) were detected in the culture media of CD14+ cells from patients with advanced disease, the production of these cytokines was abolished after treatment and tumor regression." (PMID 32824016, 2020). "CD14+ DCs infiltrate both primary and metastatic tumour sites, and may attenuate the efficacy of anti-cancer immunotherapies." (PMID 32488012, 2020). "Given the prominent role of IL-10 in tumor immunology and the emerging role of CD14+HLA-DRlowMDSC in human diseases, these findings may also have a biologically significant counterpart." (PMID 31316520, 2019). "In addition, macrophage co-culture with TRAMP-C2 cells at acidic pH was associated with an increase in the release of inflammatory and angiogenic cytokines/chemokines (e.g. VEGF, CD14, M-CSF) known to be involved in tumour progression." (PMID 31417189, 2019). "In addition to the examples cited in Section 2.3, in a mouse model of pancreatic cancer, tumor cells converted CD14+ peripheral blood monocytes into monocytic MDSCs, which in turn induced tumor cell EMT." (PMID 31096701, 2019). "As CD14+ monocytes lose HLA-DR expression and thus convert from an inflammatory to an anti-inflammatory phenotype, they play a role in subverting effective anti-tumor responses, and their abundance in patient blood inversely correlates with favorable outcomes." (PMID 31191529, 2019). "Noteworthy, it has been reported that an increase in the frequency of CD14+CD169+ cells may be associated with the development and progression of CRC and a concomitant rise of both pro-tumor (M2) and anti-tumor (M1) monocytes and infiltrating macrophages." (PMID 29690889, 2018). "To determine whether LUSC CD14 expression arose from tumor cells and/or tumor-infiltrating leukocytes, we performed immunohistochemistry (IHC) on a LUSC tissue microarray (TMA) previously characterized by subtype 8." (PMID 29777108, 2018). "Furthermore, addition of CD14+ cells to tumor spheroids on day 3 resulted in infiltration of monocytes into spheroids in less than 24 hours." (PMID 30400822, 2018). "In addition, there are positive correlations of Tim-3 expression on CD14+ monocytes with tumor grades and Tim-3 expression on TAMs with poor prognosis in HCC patients." (PMID 30309387, 2018). "Coculture of circulating naïve human monocytes/macrophages and lymphocytes with tumour cells from patients with proficient mismatch repair CRC induced both an alternative phenotype with higher expression of PD-L1 in CD14+ cells and the T-cell exhaustion phenomenon." (PMID 30285662, 2018). "This seems contradictory; a rise of leukemic cells could be considered as an increased tumor-size, which could result in an increased tumor-induced differentiation of monocytes towards BDCA1+CD14+ cells." (PMID 30235890, 2018). "In addition, tumor-derived exosomes can activate differentiation of CD14+ monocytes into CD14+ HLA-DR-/low cells, which suppress the differentiation and cell lysis ability of T cells." (PMID 28659795, 2017). "In both HCC and HNSCC, MDSCs defined as CD14+ with low HLA-DR were detected in the tumor tissue." (PMID 28220123, 2017). "We have shown that lactic acid, a side product of glycolytic energy production, accumulated in dense MoDC cultures and played an important role in reducing the development of IL-12-producing CD1a+CD14− DCs16, similarly as it has previously been shown in MoDCs developing in tumour microenvironment." (PMID 28276533, 2017). "Beside the BC cells, a tumor-associated population of CD45-positive leukocytes (60%; range 4–96%) was identified in all CSF samples, represented by lymphocytes (61%; range 6–85%) and monocytes (CD14 positive = 18%; range 6–57%)." (PMID 28399903, 2017).
tumor (continued). "Tumor-derived sCRT39-272 should be able to help sustaining such an inflammatory microenvironment because of its potent ability to elicit proinflammatory cytokine production by monocytes/macrophages via CD14/TLR4 as documented by our previous work." (PMID 29075268, 2017). "However PD-L1 on CD45+CD14+mononcytes/macrophages in tumor tissue show a significantly higher level compared with that in adjacent nontumor tissues." (PMID 28061450, 2017). "Analysis of intra-tumor cytokine transcription levels suggests that AAT administration promotes a pro-cytotoxic inflammatory profile inside the tumor, including elevated transcription levels of IL-12p40, CD14, and IFNγ, and reduced transcription of IL-1Ra, VEGF, and α-SMA." (PMID 28003813, 2016). "Reduction of circulating CD14+ monocytes might anticipate a migration and subsequent differentiation of monocytes into tumor tissue." (PMID 27507056, 2016). "Indeed our data show that most of the factor-producing transcripts that changed upon FAP vaccination originated from tumor infiltrating leukocytes and CD14+ cells." (PMID 26943036, 2016). "CD14 is a multifunctional receptor and contributes to different biological and pathophysiological processes including apoptosis, sepsis, inflammatory diseases, angiogenesis and tumor growth." (PMID 26437765, 2015). "In primary tumor tissues, both OS and ES tissues had limited tumor-infiltrating lymphocytes but 87 % of OS tissues (n = 8) had a significant (>50 %) CD14+ cell infiltration while 83 % of ES tissues (n = 6) had less than 25 % CD14+ cell infiltration." (PMID 26286851, 2015). "Thus, CD11b+, CD14+ monocytes from patient blood and tumor tissue were referred to as “TEM” and compared with respect to receptor and cytokine expression." (PMID 25768678, 2015). "Therefore, CD14 has been demonstrated to be a candidate for developing anti-cancer medications in tumor growth and angiogenesis." (PMID 26437765, 2015). "Since FOXP3 expression correlated to CD14 expression, the presence of macrophages or dendritic cells expressing CD14 may be responsible for the activation of effector T cells, which in turn limited tumor progression." (PMID 26161395, 2015). "Interestingly, flow cytometry indicated that HER2 expression was higher on the patient’s tumor-infiltrated CD14+ cells than the CD14+ PBMCs (19.3% and 1.29%, respectively)." (PMID 25655677, 2015). "The increased frequency of CD14+CD169+IL-10+ macrophages in tumor tissues may create a protumor immunosuppressive microenvironment to promote the progression of CRC." (PMID 26509874, 2015). "Cells in the tumor bed were assessed by flow cytometry analysis for CD14+/CFSE+ expression." (PMID 26155942, 2015). "Thus, we are interested in further investigating how the CD14+CD169+ macrophages in the tumor microenvironment regulate the progression and metastasis of CRC." (PMID 26509874, 2015). "All these characteristics indicate that CD14+CD16+ monocytes have protumorigenic features and might be associated with rapid tumor progression and poor patient outcome." (PMID 25280428, 2014). "CD14+ cells were isolated from tumor cells after coculture and Western blotting was performed." (PMID 24652403, 2014). "Alternatively, an up regulation of this cell type might be a sign of the malignant disease itself, as intermediate monocytes including CD14+CD16+ cells had been enhanced in tumor patients." (PMID 24330813, 2013). "This heterogeneity, evident in the histologic features of the harvested tumor tissue and in the in vitro studies of the CD14+ cell fractions, may have also contributed to the variable functional properties of the stromal cell isolates." (PMID 23922683, 2013). "Both DC-SIGN and BDCA3 may thus contribute to the immune-suppressive activity of tumor-modulated CD14+ cells." (PMID 24324467, 2013). "Moreover, S100A9 in CD11b+CD14+ monocytic MDSC correlates with tumour response to platinum-based chemotherapy with low CD11b+CD14+S100A9+ having longer progression-free survival." (PMID 26464846, 2013).
tumor (continued). "Our results revealed that cells overexpressing CD14 exhibited antitumor potential, including significantly decreased clonogenic ability, proliferation, metastatic invasion, as well as enhanced apoptosis, suggesting a tumor-suppressive role of CD14 in the cells." (PMID 23338226, 2013). "Accompanying the tumor-associated shifts in the CD1a/CD14 frequencies, CD83 frequencies also shifted in concordance with a mature state of the CD1a+ DC and an immature state of the CD14+ DC." (PMID 23875023, 2013). "Some genes are also related to adaptive immune responses (eg, CD14) and tumor metastasis (eg, CD9)." (PMID 23717493, 2013). "The change in tumor size (mean sum of tumor diameters at post-study relative to pre-study) is significantly correlated (Spearman rank correlation coefficient ρ = -0.4) with the absolute number of monocytes (CD45+CD14+) per μl of blood at D1." (PMID 20653948, 2010). "As expected, CD45(-)/VE-Cadherin+ tumor endothelial cells were Tie2+/CD14(-)." (PMID 19545375, 2009). "Exploring factors such as changes in the neutrophil phenotype or interactions between neutrophils and TAMs after RT could lead to significant breakthroughs, and future studies will require multiplex IHC or spatial transcriptomics to dissect CD14 expression within tumor cells." (PMID 41486114, 2026). "In addition, CD14+ cDC2s showed reduced tumor antigen-specific CD8 T cell activation." (PMID 38242119, 2024). "However, whilst CD14-positive cells were detectable throughout the tumour epithelium in PCP, they were mostly observed within the reactive glia tissue, and were noticeably absent from the tumour epithelial, suggesting a specific local immune myelosuppressive phenotype in ACP." (PMID 39127699, 2024). "Considering that CD14+ cDC2s are consistently found in peripheral blood of HDs where they also display reduced T cell stimulatory capacity vs. CD14− cDC2s, the tumor-induced expansion of CD14+ cDC2s could be tumors exploiting a homeostatic system to hamper the anti-tumor T cell responses." (PMID 38242119, 2024). "Thus, the present study aimed to characterize the phenotype of macrophages (CD45+HLA-DR+CD11b+CD14+) recovered from tumor samples from patients diagnosed with GBM and submitted to immunotherapy with dendritic cells, correlating their frequency and phenotype with the survival of these patients." (PMID 38791312, 2024). "Interestingly, although major macrophage-specific mRNAs (CD68, CD14, and ITGAM) were relatively unchanged, the mRNAs associated with an M2 phenotype (CSFR1, CD163, MS4A4A, and CRC1) were decreased, suggesting a change toward a more M1, anti-tumor status." (PMID 38744944, 2024). "Considering the shared developmental trajectory for cDC2s and CD14+ DCs found here, tumor-induced CD14+ DCs might represent a cell state induced by tumor cues since they do not fulfill the requirement of a separate progenitor as defined for DC subsets in general." (PMID 38242119, 2024). "Indeed, tumor-infiltrating CD14+ DCs express high levels of CD206 and CD163 and could correspond to moDCs and/or DC3s." (PMID 37190135, 2023). "CD14+ cells present around and inside the tumor might independently predict the patient prognosis." (PMID 37071001, 2023). "The increasing levels of TME CD14+ cells were associated with a higher stage at diagnosis and the number of positive lymph nodes on pathologic evaluation but not the largest tumor dimension." (PMID 36139660, 2022). "Of note, we observed similar expression patterns for the mannose receptor CD206 (commonly used as a marker for alternatively activated, M2 macrophages) on CD14+ cells across the different tissues, indicating that M2-like phenotypes are not a specific hallmark of the tumour microenvironment." (PMID 35545675, 2022). "Thus, the threshold of ingested tumor material necessary for determination as TKTL1 or Apo10 positive CD14+/CD16+ monocytes remains unclear at this point." (PMID 36009359, 2022).